MAP4K1 (mitogen-activated protein kinase kinase kinase kinase 1)
Diseases named in the same sentence as MAP4K1 in open-access papers (continued):
Sharing a sentence is not in itself a finding about the gene and the disease.
cancer (35 papers, 2010 to 2025). A tumor composed of atypical neoplastic, often pleomorphic cells that invade other tissues. "For example, one study identified that MAP4K1 gene (encoding HPK1) was highly correlated with the expression of inhibitory receptors in a variety of cancer through database analysis, the HPK1-NFκB-Blimp1 axis may mediate CAR T cell exhaustion." (PMID 36568989, 2022). "High expression of mitogen‐activated protein kinase kinase kinase kinase 1 (MAP4K1) correlated with the severity of T‐cell exhaustion and a reduction in patient survival across multiple cancer types." (PMID 39169517, 2024). "Through the activation of the NFkB and JNK signaling pathways via MAP4K1 in cancer cells, SPIB functions as a tumor suppressor." (PMID 37684436, 2023). "MAP4K1 (Mitogen-Activated Protein Kinase Kinase Kinase Kinase 1), which is involved in multiple immune and cancer-related pathways including B cell receptor signaling, JNK, EGF/EGFR, TGF-β, and MAPK signaling, was also regulated by the five TFs." (PMID 30594216, 2018). "Other candidates, such as CD79B, MAP4K1, GRAP, TNFRSF13C, and INA, had comparable scores and are candidates for further study, as they have also been implicated in carcinogenesis of other cancer types." (PMID 28146432, 2017). "Enforced MAP4K1 expression was also shown to stimulate NFκB pathway which impeded apoptosis, resulting in resistance to cytotoxic drugs in cancer cell lines." (PMID 25904054, 2015). "MAP4K1 has been identified as a cancer immunotherapy target." (PMID 37734869, 2023). "Given that cancer cell-intrinsic MAP4K1 may serve as a tumor promoter or suppressor, revealing its functional relevance in different tumor types is crucial." (PMID 37734869, 2023). "MAP4K1 could inhibit T cell function and has been proposed as a promising target for cancer immunotherapy." (PMID 34804963, 2021). "HPK1/MAP4K1 is involved in cancer cell transformation and invasion." (PMID 27203390, 2016). "Due to the inhibitory function of HPK1/MAP4K1 in T-cell activation and the promoting effects of GLK on tumorigenesis, HPK1 and GLK dual inhibitors could be useful therapeutic drugs for cancer immunotherapy." (PMID 31640697, 2019). "We identified damaging mutations in ATR, BRCA1/2, MAP4K1, CUL3 and MAX, already reported in other cancer types but not described yet as mutated in PTC." (PMID 25803323, 2015). "Although the roles of another four genes (SCUBE2, PRKCB, IKZF1, and MAP4K1) in NPC were not known, their functions were reported in other cancer types." (PMID 33403044, 2021).
tumor (33 papers, 2008 to 2026). "In syngeneic tumor models, Map4k1 deficiency leads to rejection of intravenously injected Lewis lung carcinoma cells (LLC)." (PMID 38022587, 2023). "Another study demonstrated that combining MAP4K1 inhibition with programmed cell-death ligand 1 (PD-L1) blockade can enhance T cell responses against tumor cells with low antigenicity." (PMID 41034525, 2025). "In MAP4K1−/− mice, tumours grew more slowly, and intra‐tumoural T cells were less exhausted and more proliferative." (PMID 39169517, 2024). "It’s found that IHC signals of BNIP3, CYCS, RRAGD, CD44, EIF4E, and MAP4K1 were consistently high in tumor cells of HCC, compared with normal tissues, implying that these genes were indeed ectopically expressed in HCC." (PMID 38468074, 2024). "This study demonstrated that MAP4K1 is a regulator of T‐cell dysfunction and a potential target for enhancing anti‐tumour immune responses." (PMID 39169517, 2024). "On the contrary, other signature genes (e.g., EIF4E, MAP4K1) were shown to be highly expressed in tumor samples, supported by their functions in either mTOR or Hippo regulations." (PMID 38468074, 2024). "Mechanistically, we noticed that GBM cell MAP4K1 remodels cytokine–chemokine networks in the tumor microenvironment." (PMID 37734869, 2023). "In summary, our findings reveal that GBM cell MAP4K1 not only plays an oncogenic role in cell proliferation and tumor growth but also autonomously remodels the tumor immune microenvironment by resisting the trafficking of CD8+ TILs to tumor sites." (PMID 37734869, 2023). "Together, our findings provide novel insight into the pathological significance of GBM cell-intrinsic MAP4K1 in driving tumor growth and immune evasion by remodeling cytokine–chemokine networks." (PMID 37734869, 2023). "AMPK and TNF receptor signaling (e.g., MTOR, MAP4K1) were overrepresented in the tumor tissues of EDAC at the protein and phosphoprotein levels." (PMID 35397555, 2022). "In conclusion, these results indicated that these five risk genes (CD19, FGF2, MAP4K1, DCN and STAT6) were actually differentially expressed between normal kidney samples and ccRCC tumour samples." (PMID 31782902, 2020). "In addition, MAP4K1 contributes to tumor suppression by promoting T cell proliferation upon stimulation with anti-CD3 and anti-CD28 antibodies." (PMID 41034525, 2025). "Thus, MAP4K1 is associated with cell proliferation, survival, and cell cycle regulation of GBM cells, suggesting that GBM cell MAP4K1 plays a critical role in tumor growth and progression." (PMID 37734869, 2023). "It is known that mitogen-activated protein kinases (MAP4K1 and MAP4K4) and the insulin resistance pathway (PRKCD and PRKAB1) may be associated with tumor progression through modulation of gene expression responsible for cell cycle, proliferation, and growth." (PMID 35453789, 2022). "Accordingly, selective MAP4K1 inhibition was considered a means to enhance anti-tumor immunity." (PMID 31672930, 2019). "Results showed that the mRNA levels of BNIP3, CYCS, RRAGD, CD44, EIF4E, MAP4K1, and LIN28B were higher in tumor samples, whereas the mRNA levels of PPARGC1A and FLT3 were higher in normal samples." (PMID 38468074, 2024). "MAP4K1 activity is enhanced by prostaglandinE2 (PGE2) and transforming growth factor beta (TGFβ), immunemodulators commonly present in the tumor microenvironment." (PMID 39331123, 2024). "In multiple mouse tumour models, pharmacological inhibition, genetic depletion, or PROTAC‐induced degradation of MAP4K1 were shown to be more effective than genetic depletion of PD‐1 in CAR‐T cells in improving the efficacy of CAR‐T cell‐based therapies." (PMID 39169517, 2024). "MAP4K1 facilitates GBM cell proliferation, survival, and tumor growth by remodeling cytokine–chemokine signaling networks, including the IL-18R and IL-6R pathways." (PMID 37734869, 2023).
tumor (continued). "PIK3CD, MAP4K1, and MAPK10, which are key members of the LPS-stimulated MAPK pathway, are highly expressed in patients with high tumor burden." (PMID 33225985, 2020). "The in vivo tumor growth inhibition observed in cancer models of various cellular origin (GL261 glioma, MC38 colon adenocarcinoma, and 1956 sarcoma) supports the broad potential application of a MAP4K1 inhibitor." (PMID 38022587, 2023). "However, there are very few studies that assess the roles of non-hematopoietic cell MAP4K1 in tumor growth and progression." (PMID 37734869, 2023). "PDCD4 particularly inhibits the MAP4K1 promoter without affecting other pathways, such as ERK or NF-κB, thereby reducing tumor cell invasion." (PMID 41034525, 2025).
neurological disorders (1 paper, 2016). "Five known PKA substrates (FLNA, ACTB, SOX9, MAP4K1 and GBF1) interacted with the domain modules of NBEA and three of these are linked with neurological disorders (FLNA, ACTB, SOX9)." (PMID 26999814, 2016).
MAP4K1 also shares sentences with these, for which no sentence is quoted: lymphoma (5 papers); pancreatic cancer (5); systemic lupus erythematosus (5); Autoimmunity (4); leukemia (3); Lewis lung carcinoma (2); psoriatic arthritis (2); acute pancreatitis (1); adenocarcinoma (1); Allergy (1); and Muscular Disorder (1); B-cell NHL (1); chronic pancreatitis (1); colorectal cancer (1); diabetes (1); endometrial carcinoma (1); experimental autoimmune encephalomyelitis (1); gastrointestinal stromal tumor (1); hepatocellular carcinoma (1); intrahepatic cholangiocarcinoma (1); ischemia (1); ischemic stroke (1); lung adenocarcinoma (1); metastatic cancer (1); metastatic melanoma (1); pancreatitis (1); Parkinson disease (1); psoriasis (1); rheumatoid arthritis (1); sarcoma (1).
A further 2 diseases each share a sentence with MAP4K1 in 1 paper.